FGF2 (fibroblast growth factor 2)
Diseases named in the same sentence as FGF2 in open-access papers (continued):
Sharing a sentence is not in itself a finding about the gene and the disease.
tumor (continued). "Thus, the angiogenic phenotype may result from the production of growth factors, such as FGF-2 and VGEF, by the tumor cells and/or the down-regulation of negative modulators, like TSP-1, in tissues with quiescent vasculature." (PMID 22143687, 2012). "In addition, our results showed that the number of apoptotic cells was not increased and microvessel density was decreased after FGF2-Ad-NBS1/cisplatin treatment, suggesting successful transduction into not only tumour cells, but also ECs by the FGF2-targeted adenovirus system." (PMID 21063405, 2010).
cancer (783 papers, 1992 to 2026). A tumor composed of atypical neoplastic, often pleomorphic cells that invade other tissues. "FGF2 from cancer-associated fibroblasts stimulates the growth and progression of human BC cells through FGFR1 signaling." (PMID 40547857, 2025). "As a member of the fibroblast growth factor (FGF) family, FGF2 is a growth factor derived from cancer-associated fibroblasts that stimulate BC cell proliferation and migration." (PMID 38189813, 2024). "In the microenvironment, it was reported that the major sources of HGF, amphiregulin, IGF‐1, and FGF‐2 are fibroblasts, leukocyte populations, cancer‐associated fibroblasts, and epithelial/endothelial cells, respectively." (PMID 36416133, 2023). "As IER3 and IER3-AS1 play an important role in FGF-2 regulated pro-survival pathways, we wanted to investigate their role in cancer-associated biological processes." (PMID 36038571, 2022). "Noteworthy, elevated levels of FGF2 have been implicated in the pathogenesis of several diseases characterized by a deregulated angiogenic/inflammatory response, including cancer." (PMID 30349543, 2018). "Not unexpectedly, we observed strong associations of high levels of factors such as IL-6, IL-8, FGF-2, and sIL-2Rα with poor clinical outcomes, consistent with documented reports for chronic inflammation and cachexia in multiple cancer types." (PMID 28938541, 2017). "FGF-2 gene polymorphism has been proved to be significantly associated with the occurrence of various diseases or cancers." (PMID 28653999, 2017). "The following section reviews current knowledge of the molecular pathways associated with FGF2 signaling in cancer, which represents a critical step for the implementation of strategies toward the development of personalized cancer therapy." (PMID 27007053, 2016). "It is worth noting that in the vast majority of studies, high serum and intratumoral FGF2 levels were associated with reduced cancer patient survival." (PMID 27007053, 2016). "Diagnostic assays are used to quantify FGF2, FGFRs, and downstream signaling molecules to better select a target patient population for higher efficacy of cancer therapies." (PMID 27007053, 2016). "We further observed that the inhibitory effects of msFGFR2c was not only associated with the concentrations of ligand (FGF-2) but also with the endogenous expression of FGFRs in the different types of cancer cells." (PMID 28049184, 2016). "We found that fibroblasts induce cancer cell motility and invasion in a cell-contact dependent manner and we provide a mechanism: Fibroblasts surface associated FGF-2 activates FGFR on cancer cells, which in turn activates SRC." (PMID 25973543, 2015). "FGF2 is also overexpressed in a great numbers of human carcinomas, including PCa, and implicated in oncogenic behaviours, including invasion and migration." (PMID 26650737, 2015). "FGFR inhibition resulted in cytoplasmic localisation of FGFR1 and FGF2, in contrast to vehicle-treated conditions where PSCs with nuclear FGFR1 and FGF2 led cancer cells to invade the underlying extra-cellular matrix." (PMID 24503018, 2014). "We analyzed the expression of the 4 FGFRs and the dominant cancer-associated ligand (FGF-2/basic FGF) at the mRNA level in a panel of 30 UC cell lines by whole genome expression profiling (Illumina platform)." (PMID 23468956, 2013). "Suggestive increased risk of ER positive cancer was also observed in EAs for carriers of FGF2-rs308379 TA/TT genotypes (OR=1.41, 95% CI, 0.96-2.07)." (PMID 23991131, 2013). "Some FGFs, like FGF1 and FGF2, have potent angiogenic activity and are implicated as promoters of angiogenesis, the formation of new blood vessels, in cancer and chronic inflammatory diseases." (PMID 23469107, 2013). "Having functionally implicated FGF-2 in the angiogenic phenotype, we sought to identify the cell type in cervical neoplasias and cancer that expressed FGF-2, by using FACS." (PMID 18232728, 2008).
cancer (continued). "It has previously been shown that extracellular vesicles derived from endothelial cells (ECEVs) induce dermal fibroblasts to express a gene signature correlated with FGF2-mediated cancer associated fibroblast (CAF) activation, under the control of transcription factor ETV1." (PMID 42124642, 2026). "GPC1 is known to function as a co-receptor/modulator of various growth factors to enhance the binding to their respective receptors, and cancer-associated fibroblasts (CAFs) are an important contributor of some of those growth factors in tumors, including FGF2 and TGFβ." (PMID 38966167, 2024). "This proved that the decrease or increase of FGF2 in the nucleus may have an effect on the proliferation and invasion of cancer cells, but the cause of this phenomenon remains to be further studied." (PMID 36059652, 2022). "Furthermore, in xenografts derived from pancreatic cancer patients, the expression of FGF2 correlated with the susceptibility of the cancer cells to OV infection." (PMID 36361831, 2022). "A1-mediated altered translation has been implicated in cellular proliferation and cancer, where growth factor receptors and oncogenes like FGF-2 (fibroblast growth factor 2), MYC (c-Myc), IQGAP1 (IQ motif containing GTPase activating protein 1), and CYLD (cyclin D1) are aberrantly translated." (PMID 34439945, 2021). "Moreover, this was associated with nuclear translocation of FGF-2, thereby suggesting the potential interaction of the ligand with its nuclear targets, promoting cancer cell proliferation, growth, and invasion." (PMID 32599808, 2020). "Moreover, some dimeric FGF2 variants internalized more efficiently into FGFR overexpressing cancer cells." (PMID 32526859, 2020). "The JAK/STAT pathway has been implicated in FGF2-induced chemoresistance in human cancer cells." (PMID 27007053, 2016). "In addition, high intratumoral and serum levels of FGF2 were associated with relapse and/or recurrence in various cancers such as bladder, breast, esophageal cancers and HL." (PMID 27007053, 2016). "Together, enhanced expression of FGFR1 and FGF2 thus plays as an escape mechanism for cell survival of afatinib-resistant cancer cells, that may compensate the loss of EGFR-driven signaling pathway." (PMID 25115383, 2014). "To identify the paracrine factors responsible for T47D carcinoma cell growth stimulation we treated the co-cultures with neutralizing antibodies to eleven factors implicated in stroma-carcinoma interactions (FGF-2, HB-EGF, Heparanase-1, HGF, IGF-1, IGF-2, MT1-MMP, PDGF, SDF-1, TGF-β1, and Wnt-1)." (PMID 23056402, 2012). "Moreover, a recent study reported that carcinoma-associated fibroblasts derived from C4-HI tumors produce higher levels of fibroblast growth factor-2 (FGF-2) than fibroblasts derived from C4-HD tumors." (PMID 20520761, 2010). "Other experiments indicate that imatinib had these effects because its inhibition of stromal PDGF receptors suppressed the expression of FGF-7 (a factor that encourages epithelial cell division) and FGF-2 (a proangiogenic factor) by cancer-associated fibroblasts." (PMID 18232728, 2008). "Additionally, FGF2 and macrophages have been previously linked in cancer research." (PMID 38745238, 2024). "Most likely, FGF2 functions are cell‐ and tissue‐dependent, and more work needs to be done to link FGF2 to cell and, potentially, cancer metabolism." (PMID 41131959, 2026). "Fibroblast growth factor 2 (FGF2)—secreted by cancer‐associated fibroblasts (CAFs)—exerts protumor effects, and serine protease 23 enhances TAM infiltration via FGF2." (PMID 41426206, 2026). "Cancer Therapy: The FGF2-derived peptide FREG specifically binds to the FGF2 molecule and reduces its bioactivity by competitively inhibiting the interaction between FGF2 and FGFRs." (PMID 41155018, 2025). "We have recently demonstrated the induction of cancer stem cells from normal pluripotent stem cells exposed to fibroblast growth factor 2 (FGF2) and prostaglandin E2 for 4 weeks in vitro." (PMID 39857984, 2025).
cancer (continued). "Although we showed upregulated NRG1 and FGF2 level in the cancer cells (DTP cells), it is possible that CAFs and other types of cells actively provide ERBB family and FGFR family ligands." (PMID 39369284, 2025). "BCAM-induced proteins, previously reported to drive EMT and associated processes such as cell migration in various cancers, include AREG, CXCL1, CXCL10, EDN1, FGF2, TGFβ1 and VEGFB." (PMID 40082910, 2025). "To investigate the interaction modes and binding affinities of GC-3,5-diGA and 1,2,4,6-GA-glc with shared targets involved in cancer and oxidative stress, we conducted systematic molecular docking analyses on four target proteins: FGF2, TERT, MMP9, and ABCG2." (PMID 40363725, 2025). "The cytokines associated with the pre-cancer or the initiation stage of HCC, TGF-β, FGF2, IL-8, and TNF-α were expressed at similar levels in the HIV + participants compared to the HCC + participants." (PMID 41219858, 2025). "Both CD55 and FGF2 are known to be involved in tissue remodeling and protection, the regulation of fibroblast activity, and cancer development and immune evasion." (PMID 40725231, 2025). "We found upregulation of factors such as FGF2, POSTN, and LTBP4 in classic morphology tumors, all of which are closely linked to activated cancer-associated fibroblasts (CAFs) and ECM remodeling." (PMID 41155518, 2025). "FGFBP1 has been reported to bind FGF1 and FGF2 and enhance biological activities in carcinoma cells." (PMID 40685360, 2025). "To demonstrate the role of JAK-STAT and CBP/p300 in regulating p21 and contributing to FGF2-promoted cancer stemness-like traits, we also evaluated the effect of UC2288, AZD1480, and SGC-CBP30 on reducing these traits within the same FACS analysis." (PMID 38553760, 2024). "To show that p21 is a crucial regulator mediating the effects of FGF2 on cell proliferation in FGFR1 amplified cancer cells, we used propidium iodide (PI)-based cell cycle analysis with flow cytometry." (PMID 38553760, 2024). "Although FGF2 has been identified as an EMT activator in the progression of cancers, studies about its EMT-related regulatory mechanisms in BC are limited." (PMID 38189813, 2024). "The most significant cancer-related pathways regulated by asporin are FGF2, TGF-β1, BMP-2, epidermal growth factor receptor (EGFR) and CD44." (PMID 36765749, 2023). "The study demonstrated that the cancer-associated fibroblasts (CAFs) induced high levels of fibroblast growth factor 2 (FGF2), which enhanced the susceptibility of the cancer cells to OV infection and improved therapeutic efficacy." (PMID 37491263, 2023). "While FGF2 signalling is essential for wound healing and normal development, the activation of FGF2 signalling in cancer cells can induce a proliferative, aggressive phenotype and is a target of various cancer therapeutics." (PMID 37691350, 2023). "A similar finding was observed in primary human dermal fibroblasts (HDFs), whereby FGF-2 with TGF-β1 cotreatment, both positively and negatively regulated fibroblast transition into cancer-associated fibroblasts (CAFs)." (PMID 36980168, 2023). "Our data suggest that FGF2 signalling is a possible mechanism for mesothelial populations to provide a CAF‐like role to cancer cells, supporting the growth of cancer cells that have migrated to the pleura from the breast." (PMID 37691350, 2023). "Previously, we demonstrated the efficacy of fibroblast growth factor 1 (FGF1) and 2 (FGF2) as a targeting molecules for FGFR1-overproducing cancer cells." (PMID 37373291, 2023). "Our results confirm that the FGF2 dimer with a specific well-defined topology can serve as an effective drug delivery vehicle for targeting cancer cells that overproduce FGFR1." (PMID 37373291, 2023). "FGF2 has been related to a poor prognosis in different cancer types, including having a significantly increased expression in BM biopsies from AML patients." (PMID 37932837, 2023).
cancer (continued). "The CAFs_c2_DCN subcluster promoted cancer cell growth via the FGF2/7‐FGFR3/4 and IGF1‐IGF1R signaling pathways." (PMID 36529697, 2023). "Compared with single-drug monomeric conjugates, the dimeric FGF2 dual warhead conjugate kills cancer cells more efficiently and has the potential to limit the ability of cancer cells to develop resistance to cytotoxic drugs." (PMID 37373291, 2023). "Due to preferential binding of FGF2 and FGF4 to the IIIc-isoforms of FGFRs, the cancer cells expressing IIIc isoforms of FGFRs become sensitive to FGF2 and FGF4, which are abundant in stromal tissues." (PMID 36140527, 2022). "Abrogation CAF progenitor expansion by FGF2 inhibition can inhibit local growth and prevent distant metastasis of cancer cells." (PMID 35941662, 2022). "Zoledronic acid has direct cytotoxic activity on cancer cells, suppresses angiogenesis, inhibits the FGF-2- and VEGF-dependent proliferation of endothelial cells, and inhibits VEGFR-2 in an autocrine cycle." (PMID 36362718, 2022). "An elevated production of FGF-2 was shown to support a malignant cancer phenotype and chemotherapy resistance by activation Ras-MAPK and PI3K pathways." (PMID 36012769, 2022). "The functional link between FGF-2 signalling and its downstream target genes, including lncRNAs, is largely unexplored in normal and cancer cells." (PMID 36038571, 2022). "Another factor attenuating CD8 T cell infiltration is Fibroblast growth factor-β (FGF2) a cytokine released by cancer cells that activates quiescent fibroblasts and upregulates CAF marker expression like αSMA and FAP." (PMID 35479076, 2022). "Enrichment of several common cancer associated pathways in the FGF-2 treated HEK293 and HeLa cells indicate a strong link between the FGF-2 signalling cascade and cancer." (PMID 36038571, 2022). "We investigated the significance of FGF-2/IER3-AS1 regulated CC and CXC chemokines in the regulation of cancer associated biological processes such as cell proliferation, pro-survival pathway regulation and cell invasion." (PMID 36038571, 2022). "Fibroblast growth factor 2 (FGF2) is a key player in cancer and tissue homeostasis and regulates renewal of several stem cell types." (PMID 36505741, 2022). "Cancer cells release inflammatory mediators as well as pro-angiogenic factors, including fibroblast growth factor 2 (FGF-2), SCF, and nerve growth factor (NGF), thus activating vascular epithermal growth factor (VEGF) and SCF/c-KIT signaling among others." (PMID 35216365, 2022). "The FGFR ligand FGF2, also known as FGFb, is frequently dysregulated in a variety of cancers (for review, see Ref." (PMID 34228897, 2022). "High levels of growth factors and angiogenic cytokines, such as VEGF-A, FGF-2, TNF-α, urokinase and MMPs, are secreted by the precursors of “cancer associated fibro-blasts” (CAFs)." (PMID 36362718, 2022). "Extracellular AGR2 induces angiogenesis by binding to VEGF-A and FGF2, thus leading to migration and metastasis in cancer." (PMID 35055132, 2022). "Serum FGF2 and colony transformation were marginally significantly correlated among healthy, cancer-free females aged less than 65 years." (PMID 34685650, 2021). "One of the main inducers of EMT in many types of cancer is FGF2, which activates EMT through the MEK/ERK signaling pathway." (PMID 34830951, 2021). "The cancer-promoting activity of FGF2 can be blocked by various strategies, including ligand-binding inhibitors, tyrosine kinase inhibitors, and anti-FGFR antibodies." (PMID 34839358, 2021).